CD14 (CD14 molecule)
Diseases named in the same sentence as CD14 in open-access papers (continued):
Sharing a sentence is not in itself a finding about the gene and the disease.
tumor (continued). "High MKI67+ tumor cell percentage positively correlated with antitumorigenic cell types such as CD3+ T cells, M1-like macrophages, and CD14+HLA–DR+ mature monocytic cells independent of MMR status and other factors (all P < 0.001)." (PMID 41201451, 2026). "There was significantly higher expression of the trogocytic markers CD45, CD14, and CD16 in trogocytic tumor cell populations compared to non-trogocytic tumor cell populations." (PMID 40440354, 2025). "In the absence of CD14+ TAMs, human CD4+ T cells responded to tumor antigen with TNF production (first column)." (PMID 40872773, 2025). "The macrophage lineage was further divided into predominant populations: suppressive (SPP1+, APOC1+), pro-tumour (VEGFA+, MKI67+), inflammatory (C1QC+), classical (CD14+) and non-classical cells (CD16+)." (PMID 39788719, 2025). "did not report the direct effect of tumor cells on DC3 development, a comparison of primary blood DC3s with breast tumor infiltrating CD1c+CD14+ DCs revealed phenotypical and transcriptional alignment." (PMID 38242119, 2024). "In conclusion, we establish cDC2s and not monocytes as potential precursors of tumor-induced CD1c+CD14+ cells, and hence refer to CD1c+CD14− cells as cDC2s and CD1c+CD14+ cells as CD14+ cDC2s." (PMID 38242119, 2024). "Spatial analysis of cell phenotypes revealed that CD14+ myeloid cells and CD68+ macrophages were significantly enriched in the stromal tissue of bone metastases rather than the tumor tissue." (PMID 38193534, 2024). "In particular, three major subsets are recognized including classical (CD14+CD16−), intermediate (CD14+/− CD16low), and non-classical monocytes (CD14−CD16+), and the latter subset is considered to harbor a tumor-promoting phenotype." (PMID 37259170, 2023). "Tumor cells lacked LSEC markers (e.g., CD14) but had bimodal hepatoblast and cholangiocyte marker expression (e.g., the CK19 gene KRT19)." (PMID 36845728, 2023). "The existence of CD14+ DCs was observed in peripheral blood and tumor tissues of HCC patients irrespective of tumor stages." (PMID 36613878, 2022). "High frequencies of non-classical CD14− CD16+ monocytes and intermediate CD14+ CD16+ monocytes were closely correlated with lower tumor burden at baseline." (PMID 34071888, 2021). "mRNA levels of PCNA, DAXX, laminin and CD14 in tumour tissue were equal to the levels seen in the non-tumour tissue whereas protein expression was increased for PCNA and decreased for laminin and CD14 in the tumour tissue relative to the non-tumour tissue." (PMID 33906633, 2021). "Flow cytometry analysis showed the cells isolated from tumor tissues were all positive for CD73, CD90 and CD166, and negative for hematopoietic markers of CD14, CD19, CD34, CD45 and HLA-DR." (PMID 33744858, 2021). "In contrast, CD14 and CD163 expression were not restricted to invading TAMs and were upregulated by tumor microglia." (PMID 34286275, 2021). "We detected a large number of CD14+ monocytes/macrophages with an alternative phenotype (CD64+CD163+) and CD4+ lymphocytes that infiltrated the tumour, but not the peritumour area." (PMID 30285662, 2018). "The mutation was found in the CD3dim/CD4+ population, corresponding to tumor T cells, but not in the CD3high/CD4+; CD3high/CD8+ and CD14+ normal cell populations." (PMID 28881727, 2017). "RC cells had the following immunophenotype: positive for CD10, CD19, CD20, CD22, CD38, CD43, CD44, and CD79b and negative for CD3, CD4, CD5, CD8, CD11c, CD14, CD30, CD56, and CD200, which was identical to the primary tumor cells." (PMID 26515759, 2015). "Although efforts were made to stain the CD14+ and CD56+ tumor infiltrated immune cells, satisfactory staining was not achieved (most likely due to the use of inappropriate antibodies)." (PMID 25655677, 2015). "The CD14++CD16+ subset exhibited enhanced cytotoxicity, though nonsignificant, towards tumour cells in vitro." (PMID 23180014, 2013).
tumor (continued). "Tumor immunophenotype was characterized by a strong expression of conventional myeloid antigens (CD13, CD33, CD15, MPO), although no monocytic (CD14, CD64, CD11c, CD11b, lysozyme), megakaryoblastic (CD61, CD41) and lymphoid (CD7, CD19, iCD79a, CD56, CD2) markers were found." (PMID 36980947, 2023). "Soluble factors secreted by human renal carcinoma tumor cells and pancreatic cancer tumor cells have been shown to inhibit DCs differentiation from CD34+ progenitors and trigger a lineage commitment toward CD14+ monocytes lacking APC function." (PMID 36230990, 2022). "Notably, these NK cells carry, non-NK, tumor cell antigens on their surface, evidence of trogocytosis during tumor cell killing, i.e., they carry CD19 in B cell-derived cancers and CD14 in myeloid-derived cancers." (PMID 31998309, 2019). "Finally, a multivariate analysis indicated that tumor grade G3 and high IL-6/c-FLIP+PD-L1+CD14+ cells were negative independent prognostic factors for both OS and DFS in this patient’s cohort." (PMID 30518925, 2018). "Due to the increased relevance of immune system components in the tumour microenvironment, we first studied the presence and phenotype of infiltrated CD14+ monocytes/macrophages, and CD4+ or CD8+ T-lymphocytes, noting that the tumour zones were significantly enriched in CD14+ cells." (PMID 30285662, 2018). "In this context, after 120 h of interaction, CD14+ monocytes/macrophages showed an alternative phenotype (high expression of CD64 and CD163) as well as higher levels of PD-L1 than naïve controls, which did not have any contact with tumour cells." (PMID 30285662, 2018). "Our next objective was to investigate macrophage populations in the breast TMA by first analyzing the expression of CD14 (monocytes), CD68 (all macrophages), and CD163 (M2 macrophages), and further stratifying the expression of these markers within PDLIM2-positive and -negative tumours." (PMID 36531051, 2022). "To determine whether soluble factors might be responsible for cDC2 conversion, we exposed cDC2 DCs to conditioned media (CM) collected from BLM tumour cells and OMC, and observed that both CM drove the conversion of freshly isolated cDC2 into CD14+ DCs, as opposed to control medium." (PMID 32488012, 2020). "The SRH cell line is derived from a mesenchymal tumor that is reflected by cell surface expression of mesenchymal markers, including CD10, CD44, CD73, CD90, CD105, CD146, and CD166 concomitant with the lack of the hematopoietic lineage surface markers CD14, CD19, and CD45." (PMID 33322555, 2020). "Interestingly, CD14−SIRPαlow cells exhibited properties of typical Mo/MΦs similar to CD14+SIRPαhi cells, but lacked CD163 expression, gained CD16 expression, migrated less and phagocytosed tumor cells less efficiently, yet stimulated rather than suppressed T-cell function." (PMID 31611550, 2019). "Eight other immune subsets, including naive CD4+ T cells, Lag-3+/−CD8+ T cells and CD14+macrophages, showed no significant enrichment in neither tumour groups, although CD27− B cells with unknown functions were also significantly enriched in tumours with low immune-ITH." (PMID 33431814, 2021).
infection (527 papers, 2004 to 2026). The state of being infected such as from the introduction of a foreign agent such as serum, vaccine, antigenic substance or organism. "The right panel shows the cellular changes in the state of HMGN2-deficiency: under the same infection conditions, histone modification in the CD14 gene promoter region of macrophages is altered, promoting the upregulation of CD14 expression." (PMID 41246296, 2025). "For example, (TRAV1-2+CD8+) MAIT cells, (NCAM1hiCD160+) NK cells, (CD4loCSF1R−CD33−CD14+) classical monocytes, and (CD33− HLA-DMA-CD14+) classical monocytes were associated with asymptomatic infection." (PMID 37795240, 2023). "In TLR4-deficient mice, recruitment of CD14+ and NK cells was diminished upon infection while viral clearance was delayed." (PMID 37896776, 2023). "Both complement system activation and CD14 antigen expression pattern are associated with monocyte exhaustion in sterile and infection-induced inflammation, with life-threatening consequences for the patients." (PMID 36059503, 2022). "Soluble CD14 (sCD14), a marker of immune activation, was found to be significantly associated with both the infection frequency (P < 0.01) and the genetic diversity of the genetically-intact HIV proviruses (P = 0.05)." (PMID 35916523, 2022). "Studies with CD14-deficient mice, however, demonstrated that, in the presence of high levels of LPS, as it occurs in an acute and rapid infection, the contribution of CD14 in promoting the binding of LPS to TLR4 is negligible." (PMID 36142813, 2022). "In agreement with previous reports, we found that CD14+ monocytes are susceptible to infection by both ZIKV and DENV." (PMID 34160241, 2021). "Strikingly, we observed a significant association between the frequency of HLA-DR− CD14+ cells after the DNA prime (week 6) and the number of challenges to infection (P = 0.0006, R = −0.816, Spearman test." (PMID 31139193, 2019). "In vitro infection model studies on monocytes and macrophages have shown a role of CD14 or its associated molecules in DENV mediated infection, as pre-treatment of these cells with LPS before DENV infection suppressed the infection markedly." (PMID 31489877, 2019). "Successful infection of both CD14+ and CD34+ cells has been linked to interactions between the virion and EGFR." (PMID 29547547, 2018). "We analysed virally encoded miRNA expression in CD34+ and CD14+ cells at 4 days post infection (dpi) with TB40 IE86-YFP." (PMID 27491954, 2016). "In a third experimental setting, infection of CD14+ monocytes resulted in an association of the MIEP with tri-methylated histone H3K27, which represents a typical marker for repressive chromatin." (PMID 26057166, 2015). "It has been described that PRRSv infection causes an increase in CD14+ expression throughout the early stage of infection, due to a rise in CD14+ monocytes that differentiate to macrophages and migrate to bronchoalveolar spaces." (PMID 26159815, 2015). "Three skin DC subsets were susceptible to DENV-2 infection ex vivo: LCs and CD14+ DCs were infected most efficiently while CD1c+ cells showed a lower infection rate." (PMID 25474532, 2014). "In models of gut infection, rabbits treated with a neutralizing anti-CD14 antibody exhibited a remarkably higher susceptibility to infections with Shigella, the cause of bacillary dysentery." (PMID 23898465, 2013). "CD-14 associated molecule is necessary for the cellular response in infections mediated by bacterial lipopolysaccharide, which activates monocytes for the expression of cytokines, growth factors, and procoagulatory factors." (PMID 22140591, 2011). "Decidual CD14+ cells were susceptible to infection by HIV-1BaL (ranging from 1700 to 6280 pg p24 Ag/ml), but were not permissive to HIV-1LAI (max = 150 pg p24 Ag/ml)." (PMID 19543402, 2009).
infection (continued). "Curiously, our data showing that loss of CD14 molecule associated with protection from ECM is somewhat in conflict with a previous study in which 100% of mice deficient for the CD14 gene developed fatal ECM within 6 to 8 days after infection with 106P." (PMID 19710907, 2009). "Further investigation in mice deficient for the CD14 gene revealed that loss of CD14 had a dual effect following infection with Pb-A parasites." (PMID 19710907, 2009). "Those with the CD14 -159CC genotype had a significantly increased risk of early infection with P.aeruginosa suggesting that CD14 C-159T plays a role in determining the risk of early infection with P.aeruginosa." (PMID 15975149, 2005). "tBHQ upregulated mRNA expression of many receptors that are involved in virus entry, such as Anxa2 and FPR-RS2 (Anxa1) receptors (they bind virus associated Anxa proteins that promote infection of the host cell) and other “minor” receptors, e.g., Cd14 and Mgl1." (PMID 35629310, 2022). "The RuV infection-associated reduction in CD14 expression could support its course of infection in MΦ and potentially contribute to the in vivo persistence of RuV in M2 MΦ." (PMID 35203475, 2022). "CD14 is associated with many diseases and plays a dual role in host resistance to infection." (PMID 36552219, 2022). "A subset of CD14+ cells was shown to distinctly change its transcriptional state in bacterial sepsis, in severe Covid-19 infection, and also in sterile infection caused by trauma, thus delaying the recovery and increasing the likelihood of developing complications." (PMID 36059503, 2022). "In addition, we found a decreased frequency of total monocytes with an increased PD-1 expression on CD14+ monocytes in severe/critical patients in association with the time of infection." (PMID 35971391, 2022). "We can observe that the CTSG levels are significantly higher in the supernatants of MAP-infected CD14+-MDMs obtained from cows carrying the C allele (1.85 ± 0.11 ng/mL) after 2 h of infection than in infected CD14+-MDMs from cows with the AA genotype (1.68 ± 0.06 ng/mL) (p = 0.008)." (PMID 36359162, 2022). "The infection in macrophages and the enigmatic CD14+CD163+ cells with the pathogenic Alfort-187 strain at 36 h post-infection might bias a pro-inflammatory environment, which could prevent an efficient T cell stimulation." (PMID 34445493, 2021). "In addition, T. cruzi strains have been associated with severe and mild infections and profoundly affect the response of CD14+ monocytes, inducing an inflammatory or regulatory profile in these cells, respectively." (PMID 33146244, 2020). "Additionally, we discovered a novel subpopulation of CD14+ monocytes associating with the acute phase of infection that expressed high levels of CCR4, CXCR3, and CCR6, among other markers." (PMID 30150281, 2018). "Our data predict that the infection-susceptible subset of CD14+ cells could be identified based on those with an increasing frequency of mC46 protein expression at the cell surface over time following SHIV challenge." (PMID 26958575, 2016). "An infection in the gut may cause an influx of CD14+ inflammatory DCs that release IL-12, resulting in the conversion of ILC3s into ILC1s." (PMID 28536374, 2016). "CD14+CD16+ monocytes are highly susceptible to infection with HIV." (PMID 23922698, 2013). "Because most of the HIV-1 positive cells were much larger than T-lymphocytes and exhibited a morphology similar to myeloid cells, we stained the cells for the myeloid cell marker CD14 at day 7 post infection in order to determine the susceptibility of this lineage to HIV-1." (PMID 22174685, 2011). "We investigated whether polymorphisms in CD14, the lipopolysaccharide receptor, increase the risk of early infection." (PMID 15975149, 2005).
infection (continued). "The decreased levels of CD14 in the infection foci of our model, the peritoneum of P2X7-deficient mice, could be then the cause of the increased to bacterial dissemination from peritoneum and infection of distant tissues and organs, thus compromising animal viability." (PMID 33135636, 2020). "Given the strongly contrasting associations of these sub‐communities with the phase of infection, these data suggest that unappreciated heterogeneity within CD14+ monocyte phenotypes may enable different roles for sub‐communities of these monocytes during CHIKV infection." (PMID 30150281, 2018). "Aside from the role of CXCR7 in CXCL12-guided cell migration across the blood brain barrier (BBB), the higher CXCR7 cell surface expression on the HIV-susceptible CD14+ CD16+ monocytes might increase the likelihood of CXCR7 coreceptor use in subsequent infection cycles of CD14+ CD16+ monocytes." (PMID 29560468, 2018). "The current study demonstrates that HES treatment downregulates CD14 expression on infiltrated cells in the intestinal tissues of A. hydrophila-infected mice and this may then reduce the inflammatory response caused by infection in such tissues." (PMID 24891765, 2014). "Since we observed robust transcription at 5 days post infection of CD14 (+) monocytes, we wanted to determine if virion associated transcripts could be detected from UV inactivated virus at 5 days post infection and evaluate the ability of virus encoded mRNAs to persist in CD14 (+) monocytes." (PMID 23717203, 2013). "The results showed that the upregulation of CD14 in PAMs during the early stages of infection was induced jointly by ASFV and ApoBDs containing ASFV." (PMID 40503879, 2025). "As expected, heat-inactivated ASFV, which had lost infectivity, still induced an increase in CD14 transcription in the early stages of infection." (PMID 40503879, 2025). "We also differentiated CD14+ monocytes into macrophages using M-CSF or GM-CSF (M-MФ or G-MФ) to simulate infection-driven monocyte recruitment and differentiation." (PMID 40399309, 2025). "In CD14+ cells, during latency, cmvIL-10 and LAcmvIL-10 were detected at much lower levels than in lytic infection in MRC-5 cells." (PMID 40284944, 2025). "Upon stimulation of monocytes and macrophages by microbial components via Toll-like receptor (TLR) signaling pathways during infection, CD14 is cleaved and released into circulation as presepsin." (PMID 41169360, 2025). "A strong innate response, characterized by mobilization of activated CD14+ CD16+ monocytes during the first days of infection, was detectable even in patients with mild disease." (PMID 40154795, 2025). "A reduction in HMGN2 expression in macrophages during the infection process can enhance phagocytic activity and bacterial clearance by facilitating Cluster of differentiation 14 (CD14)-mediated nitric oxide (NO) release." (PMID 41246296, 2025). "The proportion of CD14+ cells (monocyte marker) in culture decreased steadily with infection, dropping from ~95% at 24 h to ~ 75% by 72 h (p < 0.0001 at 72 h vs. control)." (PMID 41012666, 2025). "Flow cytometry analysis confirmed that PNAG induces the formation of CD14+CXCL10+ monocytes that migrate to the site of infection and trigger the innate immune response against S. aureus." (PMID 40745039, 2025). "CD14, which is expressed on the surface of myelomonocytic cells or released in a soluble form, mediates a variety of activities in response to infections." (PMID 40100809, 2025). "An immunological profile study of pediatric patients with CHIKV infection reported an increase in the number of CD14+CD16+ intermediate monocytes during the acute phase of infection." (PMID 41012652, 2025). "We also showed that PNAG induces the formation of CD14 + CXCL10+ monocytes that can migrate to the site of infection, triggering an innate immune response against S. aureus." (PMID 40745039, 2025).